E2F1 (E2F transcription factor 1)
Diseases named in the same sentence as E2F1 in open-access papers (continued):
Sharing a sentence is not in itself a finding about the gene and the disease.
glioblastoma (continued). "Glioblastoma cells treated with dBET6 exhibit significant depleted chromatin occupancy of BET proteins, reduced RNA-pol2 activity and impaired transcription program regulated by E2F1." (PMID 35702740, 2022). "Next, we found that E2F1 expression was upregulated in glioblastoma tissues from 34 patients, and a negative correlation between E2F1 expression and miR-485-5p expression was observed in glioblastoma tissues from 34 patients." (PMID 34726120, 2021). "Regarding the first signature network component, hsa-mir-137, hsa-mir-330, hsa-mir-149, hsa-mir-107, hsa-mir-181b were among the miRNAs whose experimentally validated targets (such as CTBP1, CDC42, CDK6, E2F1, VEGFA, AKT1, KAT2B) affect the pathways which play a crucial role in glioblastoma biology." (PMID 28045122, 2017). "Expression of E2F1 and E2F6 was previously reported to be higher in glioblastomas (using TCGA dataset) compared to non-neoplastic brain tissues, which we validated in the REMBRANDT dataset." (PMID 35228525, 2022). "Therefore, to identify a potential upstream regulator miRNA of E2F1 in glioblastoma, we intersected the significantly downregulated miRNAs from the GSE103229 data series (screening criteria: P < 0.05 and logFC≤-2) and the predicted miRNAs that could regulate E2F1 by TargetScan algorithm." (PMID 34726120, 2021). "Finally, we analyzed existing ChIP-sequencing (seq) data from the Encode consortium, which demonstrated direct binding of FOXM1, ETS1, E2F1, and E2F6 to the EIF4EBP1 promoter region, exon 1 and intron 1 (−1500 to +1000) in various normal and cancer cells, however not including glioblastoma cells." (PMID 35228525, 2022).
liver cancer (40 papers, 2015 to 2025). An epithelial or non-epithelial malignant neoplasm that arises from the liver. "c-Myc and E2F1 have been implicated as positive NS regulators in mice and human liver cancer cells, respectively, whereas C/EBPα and p300 have not yet been linked to NS expression." (PMID 39259742, 2024). "Here, we identified by proteome-wide analysis that KPNA2 is required for maintaining stathmin overexpression in liver cancer cells and dissected the underlying regulatory mechanism involving the nuclear import of the transcription factors E2F1 and TFDP1." (PMID 31783876, 2019). "Collectively, these results suggest that CsESPs upregulate CD24 expression via transcriptional regulation of E2F1, thereby promoting proliferation and inhibiting apoptosis in liver cancer cells." (PMID 40830893, 2025). "The therapeutic approach with targeting liver proliferation is also supported by several reports showing that cell cycle proteins CDK4, Cyclin D3, E2F1, and liver cancer promoting protein Gankyrin play a critical role in development of NAFLD." (PMID 37967813, 2024). "On the other hand, previous literatures revealed that CDCA8 affects liver cancer progression through E2F1 and ATF3." (PMID 36639822, 2023). "Upregulation of the E2F1 and STMN1 proteins has been linked to poor outcomes in liver cancer patients." (PMID 36127700, 2022). "E2F1 has also been shown previously to increase cancer cell invasion and reduce apoptosis in liver cancer and therefore, has oncogenic activities." (PMID 33868788, 2021). "Western blot analysis suggested that the expression of E2F1 was higher in all liver cancer cell lines relative to that of normal liver cells, in which cisplatin-resistant cell line HUH-7/DDP was the highest." (PMID 33868788, 2021). "In liver cancer, a significant positive correlation between the expression level of E2F1 and the level of tumor apoptosis has been reported, suggesting that E2F1 can play a tumor-suppressive role through proapoptosis." (PMID 33986804, 2021). "Collectively, we provided solid evidence, through patient tissues and cell and animal models, that FER1L4 promoted liver cancer by downregulating miR-106a-5p and miR-372-5p, thus leading to an increased expression of E2F1 and NF-κB pathway." (PMID 33868788, 2021). "In conclusion, FER1L4 promotes drug-resistant liver cancer progression through the inhibition of the expressions of miR-106a and miR-372-5p, leading to the upregulation of E2F1 and the activation of NF-κB." (PMID 33868788, 2021). "Activated E2F oncogenic signaling was always seen in the progression of liver cancer, and studies have shown that dosage-dependent copy number gains in E2F1 and E2F3 drive HCC." (PMID 31926109, 2020). "E2F1 has been studied using mouse models of liver cancer to show its role in the cell cycle during cancer progression, C6 in vivo and in vitro studies has shown its role in apoptosis in multiple human cancer cell lines." (PMID 31275738, 2019). "In summary, in this study we report that HULC is able to promote the tumor angiogenesis through miR-107/E2F1/SPHK1 signaling in liver cancer." (PMID 26540633, 2016). "Taken together, we conclude that HULC promotes tumor angiogenesis in liver cancer through miR-107/E2F1/SPHK1 signaling." (PMID 26540633, 2016). "The transcription factor E2F1 is involved in the up-regulation of many classic oncogenes, such as c-Myc in liver cancer." (PMID 26540633, 2016). "Our results indicate HOTAIR causes microsatellite instability (MSI) and abnormral expression of cell cycle related gene, e.g. CDK2, CyclinE, CDK4, CyclinD1, PCNA, ppRB, E2F1 in liver cancer stem cells." (PMID 26172293, 2015). "Here, the authors show that E2F1 is deubiquitinated by POH1 and that this enhances the role of E2F1 in cell survival, and contributes to the pathogenesis of liver cancer." (PMID 26510456, 2015). "We further validated the downregulation of E2F1 expression by POH1 knowdown in different liver cancer cell lines." (PMID 26510456, 2015).
liver cancer (continued). "The restoration of E2F1 or Survivin expression in liver cancer cells substantially counteracted POH1 deletion-induced cell growth inhibition and apoptotic response." (PMID 26510456, 2015). "Simultaneously, we observed a dysregulation in the expression of miR-187-5p in liver cancer cell lines, which may be attributed to transcriptional inhibition through the E2F1/FoxP3 axis." (PMID 37531206, 2023). "Through the construction of a protein interaction network and screening and verification of core targets, it was found that CDK1, SRC, CDK4 and E2F1 mRNA and protein expression levels were overexpressed in liver cancer tissues compared with normal liver tissues." (PMID 36699068, 2022). "In conclusion, the results indicated that FER1L4 could inhibit the expression of miR-106a-5p/miR-372-5p, to activate E2F1-mediated NF-κB pathway, leading to drug resistance in liver cancer." (PMID 33868788, 2021). "Overexpressing E2F1 activated the NF-κB pathway, leading to the progression of liver cancer." (PMID 33868788, 2021). "We experimentally demonstrated that lactate activates E2F1-mediated gene transcription by inducing E2F1 protein accumulation in liver cancer cells, and that E2F1 depletion impairs lactate-induced cell motility concomitantly with the deregulation of tubulin structures." (PMID 30813560, 2019). "In summary, we propose that the aberrant upregulation of nuclear POH1-mediated E2F1 stabilization is an important event in the development of liver cancer and that targeting POH1 might serve as a promising strategy for cancer treatment." (PMID 26510456, 2015). "Furthermore, more attention was focused on whether the NF-κB pathway is involved in the modulation of E2F1 on liver cancer cells." (PMID 33868788, 2021). "We further verified the increased expression of Sox4, E2f1, Trpv4, and Trim6 in DEN-induced, Srsf3 KO liver cancer tissues by qRT-PCR." (PMID 40568073, 2025). "Meanwhile, the interaction of E2F1 and STMN1 was ascertained by ChIP assay and dual luciferase assay in HCC and liver cancer." (PMID 35186166, 2022). "Similarly, in liver cancer, E2F1 and E2F3 were over-expressed, and synergistically induced the spontaneous development of liver cancer in mice." (PMID 35764946, 2022). "The POH1-mediated regulation of E2F1 expression strengthens E2F1-downstream prosurvival signals, including upregulation of Survivin and FOXM1 protein levels, and efficiently facilitates tumour growth of liver cancer cells in nude mice." (PMID 26510456, 2015). "Furthermore, E2F1 inhibition by siRNAs almost entirely abolished POH1-mediated upregulation of Survivin and FOXM1 in liver cancer cells." (PMID 26510456, 2015). "The E2F1 gene was moderately expressed in normal liver tissue and highly expressed in liver cancer tissue; The CDKN1A and CDK6 were not expressed in liver cancer tissues or normal liver tissues." (PMID 36699068, 2022).
neuroblastoma (36 papers, 2007 to 2025). Neuroblastoma (NB) is the most common solid, extracranial childhood tumor. "High expression of MYCN, PRMT5 and E2F1 in neuroblastoma cells derived from high‐risk disease causes a deregulated alternative RNA splicing programme and resistance to cell death." (PMID 39021294, 2025). "Previously, using TARGET and GSE85047 datasets, we had shown that transcription factor E2F1 was associated with the poor overall survival of neuroblastoma." (PMID 35764946, 2022). "Similar with the results from TARGET and GSE85047 datasets, neuroblastoma patients with higher expression levels of E2F1 were associated with the lower event free survival in GSE16476 and E-MTAB-1781 datasets." (PMID 35764946, 2022). "And high expression of E2F1 was associated with poor prognosis in patients with neuroblastoma in TARGET and GSE85047 datasets." (PMID 32593299, 2020). "Higher expression levels of E2F1 or E2F3 were associated with the worse prognosis of neuroblastoma." (PMID 35764946, 2022). "The pharmacological inhibition of PRMT5, or E2F1 inactivation, restores normal splicing, rendering neuroblastoma cells sensitive to apoptosis." (PMID 39021294, 2025). "Compared with neuroblastoma patients with lower E2F1 expressions, 3865 genes were differentially expressed in pediatric neuroblastoma patients with higher E2F1 expressions in TARGET dataset." (PMID 35764946, 2022). "Identification of 234 genes were associated with E2F1 and E2F3 expressions in neuroblastoma and those genes were significantly enriched in cell cycle signaling pathway." (PMID 35764946, 2022). "Genes associated with E2F1 and E2F3 expressions in neuroblastoma were significantly enriched in cell cycle signaling pathway." (PMID 35764946, 2022). "We then constructed a risk model based on E2F1, E2F3 expression features and age of diagnosis to predict the clinical overall survival of pediatric neuroblastoma." (PMID 35764946, 2022). "Our previous results showed that E2F1 was a target of MYCN amplification and associated with the poor overall survival of neuroblastoma." (PMID 35764946, 2022). "E2F transcription factors E2F1, E2F3, E2F7 and E2F8 were all associated with the event free survival of neuroblastoma in TARGET, GSE16476 and GSE85047 datasets." (PMID 35764946, 2022). "In this study, we reveal the mechanism by which PCLAF facilitates cell cycle progression and recommend that the PCLAF/E2F1/PTTG1 axis is a therapeutic target in neuroblastoma." (PMID 35210406, 2022). "In TARGET, GSE16476, GSE85047 and E-MTAB-1781 datasets, the E2F1 expression levels were higher in neuroblastoma patients with age at diagnosis ≥ 18 months than neuroblastoma patients with age at diagnosis < 18 months." (PMID 35764946, 2022). "On the contrary, pediatric neuroblastoma patients with age at diagnosis ≥ 18 months and with higher E2F1 expression levels had the worst event free survival and overall survival than other sub-groups in TARGET, GSE16476, GSE85047 and E-MTAB-1781 datasets." (PMID 35764946, 2022). "We then assessed the associations of age of diagnosis, MYCN amplification and E2F1 expression and E2F3 expression in the prediction of the overall survival of neuroblastoma using multivariable cox regression assay." (PMID 35764946, 2022). "Then we analyzed the relationship between PCLAF and PTTG1 genes and E2F1 in the neuroblastoma database and found that E2F1 was related to PCLAF and PTTG1." (PMID 35210406, 2022). "In the further development of therapeutic strategies of neuroblastoma by targeting on E2F transcription factors, E2F1 and E2F3 should be simultaneously inhibited to achieve better clinical outcomes." (PMID 35764946, 2022).
neuroblastoma (continued). "Protease Omi facilitates neurite outgrowth by cleaving the transcription factor E2F1 in neuroblastoma cells, which is abolished by pretreatment with the specific Omi inhibitor UCF-101." (PMID 34677809, 2021). "The high expression levels of E2F1 were observed in neuroblastoma patients with MYCN amplification in TARGET, GSE19274, GSE73517, GSE49710 and GSE85047 datasets." (PMID 32593299, 2020). "MYC, E2F1 transcription factors and ribosome signaling pathway were significantly enriched in neuroblastoma patients with MYCN amplification." (PMID 32593299, 2020). "Transcription factor E2F1 was up-regulated by MYCN amplification and associated with the poor prognosis of neuroblastoma." (PMID 32593299, 2020). "Except MYC, transcription factor E2F1 was also positively enriched in MYCN amplified neuroblastoma tissues in GSE19274 and GSE85047 datasets." (PMID 32593299, 2020). "We next investigated if lncNB1, DEPDC1B, RPL35, or E2F1 is required for neuroblastoma cell proliferation and/or survival." (PMID 31690716, 2019). "It was reported that miR-17-5p and miR-106a was found to be up-regulated by N-Myc in human neuroblastomas, while the activation of N-Myc was revealed to be directly regulated by the E2F1-3 transcriptional regulators in neuroblastomas." (PMID 28947999, 2017). "Similar results were also obtained in neuroblastoma, where ectopic expression of AHR was found to downregulate MYCN (specific malignant factor of neuroblastoma) and E2F1 expression and correlated highly with the histological grade of differentiation." (PMID 27752740, 2017). "Decreased cellular proliferation and migration of neuroblastoma and squamous cell carcinoma cell lines by directly interacting with and reducing protein stability of cytoplasmic Vimentin and nuclear E2F1, respectively." (PMID 23404198, 2013). "TRIM16 exhibits tumour suppressor functions by interacting with cytoplasmic vimentin and nuclear E2F1 proteins in neuroblastoma and squamous cell carcinoma cells, reducing cell migration and replication." (PMID 23404198, 2013). "miR-149* is known to induce apoptosis by the direct inhibition of Akt1 and E2F1 in neuroblastoma cells." (PMID 22682234, 2012). "E2F1 plays an essential role in G1/S transition and directly induces the transcription and expression of N-myc in neuroblastoma cell lines." (PMID 23251571, 2012). "The same expression analysis was carried out in SK-N-JD neuroblastoma cells, which have a very low apoptotic response to activation of E2F1." (PMID 23251571, 2012). "Subsequent studies demonstrated that HMGA1 interacts with the RB protein and interferes with RB-mediated repression of E2F1 transcription and cell cycle progression in neuroblastoma cells." (PMID 22053823, 2011). "Recent studies showed that Bmi-1 is a direct transcriptional target of c-Myc in human fibroblasts and of E2F-1 in neuroblastomas." (PMID 17179983, 2007). "Furthermore, a reanalysis of a previously published study, which included 134 Stage 4S neuroblastoma patients, allowed for the identification of E2F1 as a new gene with potential oncogenic activity." (PMID 36831529, 2023). "Also, most of the genes were highly expressed in neuroblastoma patients with higher E2F1 and E2F3 expressions." (PMID 35764946, 2022). "Also, compared with neuroblastoma patients with higher expression levels of E2F1, neuroblastoma patients with lower expression levels of E2F1 had significantly prolonged overall survival in GSE16476 and E-MTAB-1781 datasets." (PMID 35764946, 2022). "In addition, we found that diminishing the expression of E2F1 can reduce the protein and mRNA levels of PTTG1, which indicates E2F1 can alter PTTG1 expression in neuroblastoma by binding to the promoter of PTTG1." (PMID 35210406, 2022).